RNU7-60P (RNA, U7 small nuclear 60 pseudogene)
Synonyms: U7.60
Gene: Small nuclear RNA gene on chromosome 12 (11,546,479 to 11,546,540, forward strand). Ensembl gene ENSG00000251747.
Homologues: Orthologues: chimpanzee U7 (100% identical), macaque U7 (89% identical), pig U7 (84% identical). Paralogues in human: RNU7-13P (89% identical), RNU7-171P (89% identical), RNU7-35P (89% identical), RNU7-52P (89% identical), RNU7-65P (89% identical), RNU7-160P (87% identical), RNU7-41P (87% identical), RNU7-57P (87% identical), RNU7-67P (87% identical), RNU7-6P (87% identical), RNU7-71P (87% identical), U7 (87% identical), and 142 more.